EZH2 (enhancer of zeste 2 polycomb repressive complex 2 subunit)
Diseases named in the same sentence as EZH2 in open-access papers (continued):
Sharing a sentence is not in itself a finding about the gene and the disease.
breast cancer (continued). "As expected, over-expression of EZH2 was found in a variety of malignancies, such as prostate cancers, breast cancers and gastric cancers." (PMID 33575212, 2020). "Aaron and his colleagues illustrated that Praja1 promotes EZH2 degradation through K48-linkage polyubiquitination and suppresses cells growth and migration in breast cancer." (PMID 33308321, 2020). "A recent report has shown that YC-1 stimulates E3 ligase c-Cbl-mediated EZH2 ubiquitination and proteasomal degradation in breast cancer." (PMID 33308321, 2020). "At present, numerous experimental results indicate that EZH2 overexpression promotes proliferation, migration and invasion of cancer cells in endometrial cancer, lung cancer, melanoma, breast cancer, bladder cancer and colorectal cancer." (PMID 32859239, 2020). "It has been shown that curcumin inhibits mammalian target of rapamycin (mTOR)—a serin/threonine kinase—and downregulates the key epigenetic regulator enhancer of zeste homolog 2 (EZH2) in tamoxifen resistant breast cancer cells." (PMID 31936346, 2020). "Our data provide valuable insights into the EZH2 role as a key epigenetic regulator of the ECM and also highlight the importance of performing preclinical studies in breast cancer that target EZH2 and LOXL4." (PMID 32754259, 2020). "The enhancer of zeste homolog (EZH2) is responsible for H3K27me3, which promotes the metastasis of cancers such as melanoma and breast cancer." (PMID 33194731, 2020). "In contrast, inhibition of EZH2 showed enhanced lipid accumulation in breast cancer cell lines and in a hepatocyte (HepG2) cell line." (PMID 32051014, 2020). "EZH2 plays a central role in mammary gland development, as well as in the initiation, progression and metastasis of breast cancer." (PMID 32942660, 2020). "It has been reported that low EZH2 expression, which reduces H3K27 methylation, promoted drug resistance in BRCA-2-deficient breast cancer cells by the regulation of genomic stability." (PMID 31065671, 2020). "The genetic deletion of EZH2 resulted in down-regulation of cyclin D1 in breast cancer and in up-regulation of p21 in ovarian cancer, thereby causing cell-cycle arrest at the G1/S phase." (PMID 33330073, 2020). "They demonstrated that ZRANB1 can bind, deubiquitinate, and stabilize EZH2, which enhances breast cancer tumorigenesis and metastasis." (PMID 33308321, 2020). "For example, EZH2 expression in cervical cancer tissue is closely related to tumor proliferation and poor prognosis; degradation of EZH2 in breast cancer tissue weakens the invasion and metastasis of tumor." (PMID 33194612, 2020). "They found that Ub E3 ligase Praja1 mediates EZH2 protein degradation through the ubiquitination-proteasome pathway in MCF7 cells (breast cancer cell line)." (PMID 33308321, 2020). "Lastly, on the molecular level, the activities of DANCR in normal, early‐ or late‐stage breast cancer cells were achieved by EZH2‐mediated epigenetic down‐regulation of SOCS3." (PMID 31860165, 2020). "In summary, our findings suggest that miR-3613-3p acts as a cancer-suppressor miRNA and serves its anti-cancer function by inhibiting SMAD2 and EZH2 in breast cancer." (PMID 33330073, 2020). "The data for EZH2 siRNA treated breast cancer cells was publicly available and downloaded for analysis (accession number GSE30670)." (PMID 33246425, 2020). "EZH2 expression and histone H3 trimethylation are elevated in ERα-positive breast cancer cells and mammary tissue of mice exposed in utero to BPA." (PMID 33330580, 2020). "Solid tumors often exhibit EZH2 overexpression, as reported in various cancer types, with adverse outcomes, including prostate cancer, breast cancer, endometrial cancer, colorectal cancer, melanoma, cholangiocarcinoma, and ovarian cancer." (PMID 33163485, 2020).
breast cancer (continued). "Based on the result of a previous study, we found that binding of zinc finger RANBP2-type containing 1 (ZRANB1) to EZH2 led to EZH2 deubiquitination, thereby stabilizing EZH2 protein expression in breast cancer." (PMID 33109776, 2020). "This is an example of AMPK as a critical pivot to connect cellular energy state and pathological development through the regulation of EZH2 phosphorylation in ovarian cancer and breast cancer cells." (PMID 33308321, 2020). "Their study also revealed that pT367-EZH2 is essential for EZH2 cytoplasmic localization in breast cancer patients." (PMID 33308321, 2020). "Here, the authors demonstrate that EZH2 regulates response to HER2-targeting therapies in breast cancer, in part, by modulating the expression of PPP2R2B." (PMID 33208750, 2020). "We found that miR-3613-3p was negatively correlated with the expression of SMAD2 and EZH2 in the breast cancer samples." (PMID 33330073, 2020). "In the MCF7 ER-positive breast cancer cells, EZH2 interacts with subunits of the SWI/SNF chromatin remodeler complex and TRIM28, forming a complex distinct from PRC2." (PMID 33327550, 2020). "At the same time, to clarify the correlation between miR-3613-3p and SMAD2/EZH2 in breast cancer, we tested tissue samples from cancer lesions and adjacent non-cancerous areas by using qRT-PCR and Western blotting." (PMID 33330073, 2020). "LINC01133 also inhibits breast cancer metastasis through EZH2-mediated regulation of SOX4 expression." (PMID 33126510, 2020). "We evaluated the correlation between EZH2 and miR-29b/30d in breast cancer cells and found an inverse correlation between miR-29b/30d and LOXL4 mRNA by starBase v2.0 analysis." (PMID 32754259, 2020). "In silico analysis of publicly available RNA and protein expression data from TCGA datasets recapitulated cell line data and JMJD6 and EZH2 were positively correlated and co-expressed in breast cancer samples." (PMID 33246425, 2020). "AKT-mediated pS21-EZH2 inhibits its methyltransferase activity by attenuating EZH2 associated with histone H3, which attenuates H3K27me3 level, increases EZH2 target genes expression, and facilitates breast cancer tumorigenesis." (PMID 33308321, 2020). "Immunohistochemical analysis of EZH2 in breast cancer supports that higher expression levels of EZH2 correlate with aggressive features and poor prognosis." (PMID 33050946, 2020). "Our findings showed that ZMYND8 is instrumental in recruiting corepressors, KDM5C, and EZH2 onto their target promotors to regulate tumor-genes in breast cancer." (PMID 33323928, 2020). "EZH2 has been shown to function as a major oncogene involved in proliferation, migration, and metastasis of breast cancer cells 39-41, but the mechanisms are poorly understood." (PMID 32754259, 2020). "NEAT1 which promotes EMT and proliferation in breast cancer, additionally promotes migration and invasion in endometrial cancer through regulation of the miR-144-3p/EZH2 axis." (PMID 33126510, 2020). "Our recent study has also confirmed that CDK1-mediated pT345-EZH2 and pT487-EZH2 facilitate EZH2 ubiquitination and subsequent degradation in breast cancer." (PMID 33308321, 2020). "LncRNA ANCR facilitates the CDK1-EZH2 interaction and enhances the phosphorylation at T345 and T487, leading to EZH2 degradation and the attenuation of the invasion and metastasis of breast cancer." (PMID 32873321, 2020). "In a study in 2018, ZRANB1 was identified as the EZH2 deubiquitinase and stabilizes EZH2 through interacting with EZH2 via its OTU domain in breast cancer cells." (PMID 32723346, 2020). "Previous studies have revealed that ZRANB1 binding to EZH2 resulted in EZH2 deubiquitination and thereby stabilized EZH2 protein in breast cancer." (PMID 33109776, 2020). "More researches show evidences of EZH2 overexpression in many other cancer types, including breast cancer, esophageal cancer, gastric cancer, anaplastic thyroid carcinoma, nasopharyngeal carcinoma, and endometrial carcinoma." (PMID 32723346, 2020).
breast cancer (continued). "LOXL4 was the direct target of miR-29b and miR-30d, and inhibition of EZH2 reduced LOXL4 expression in breast cancer cells." (PMID 32754259, 2020). "A study reported that YC-1 decreases EZH2 expression and inhibits breast cancer cell proliferation via activation of its ubiquitination and proteasome degradation." (PMID 33308321, 2020). "Colony formation and CCK-8 assays showed that cell proliferation was significantly impaired in breast cancer cells by EZH2 inhibitor treatment." (PMID 32754259, 2020). "For instance, breast cancer cell lines treated with Ezh2 inhibitors, DNZep and GSK126, showed more lipid droplets." (PMID 32051014, 2020). "Our study showed that the EZH2-miR-29b/miR-30d-LOXL4 axis was involved in the progression of breast cancer cells." (PMID 32754259, 2020). "First, in ER-positive luminal-like breast cancer cells, EZH2 was shown to have a transcriptional activation role through physical interactions with ER and β-catenin." (PMID 33327550, 2020). "For instance, we have shown that ANCR overexpression facilitated EZH2 ubiquitination to decrease the stability of EZH2 protein, resulting in breast cancer metastasis." (PMID 32929060, 2020). "We aim to evaluate the implication of miR-33b in the EMT pathway in HER2+ breast cancer (BC) and to analyze the role of EZH2 in this process as well as the interaction between them." (PMID 33014831, 2020). "EZH2 was highly expressed in breast cancer tissues (t = 9.236, P = 0.000), while DLC1 was expressed at low levels in breast cancer tissues (t = −3.238, P = 0.002)." (PMID 32725802, 2020). "We indicated that the phosphorylation of T345-EZH2 and T487-EZH2 attenuates oncogenesis and metastasis in breast carcinoma by decreasing EZH2 stability." (PMID 33308321, 2020). "In our recent publication, we have shown the enhanced expression of EZH2 playing significant role in nicotine-induced increased breast cancer progression." (PMID 30760814, 2019). "To explore and validate the previously defined role of EZH2 in breast cancer, we first investigated its expression in primary breast tissue array and different cell lines." (PMID 30760814, 2019). "EZH2 negatively correlated its target genes in adjacent normal breast tissues of breast cancer patient included in the study." (PMID 30760814, 2019). "Literature revealed that the curcumin-induced G2/M arrest, inhibiting the assembly dynamics of microtubules, and suppressed the expression of zeste homolog 2 (EZH2) gene in breast cancer cell line MCF-7." (PMID 31207976, 2019). "miR‐101 targets enhancer of zeste homolog 2 (EZH2), a marker for aggressive breast cancer, and an upregulation of miR‐101 results in decreased EZH2 levels." (PMID 30430751, 2019). "The combination therapy of AQB and 3-Deazaneplanocin A (DZNep), an inhibitor of the histone methyltransferase EZH2 was used in vitro and in orthotopic breast cancer and glioblastoma patient-derived xenograft (PDX) models." (PMID 31367244, 2019). "EZH2 can activate NF-κB targets and NOTCH1 in breast cancer cells, which has also been implicated in the transcriptional activation of gene expression in breast cancer." (PMID 30881302, 2019). "Further to check the expression of identified target genes in an EZH2 overexpressed state, we transfected pCMV-EZH2 (Addgene) in breast cancer cells." (PMID 30760814, 2019). "A wealth of evidence supports the broad therapeutic potential of NF‐κB and EZH2 inhibitors as adjuvants for breast cancer treatment." (PMID 31282094, 2019). "While overall levels of EZH1 were higher in HMECs and MDA‐MB‐231 cells, EZH1 levels were more sensitive to EZH2 inhibition in the ER+ breast cancer cell line." (PMID 31282094, 2019). "In MDA-MB-231 breast cancer cells, reduced mRNA expression of EZH2 was detected upon DZNepA treatment whereas increased expression of its target genes (except POMT2 and VGLL4) was found." (PMID 30760814, 2019).
breast cancer (continued). "Linking ANCR interaction with EZH2 to promote its phosphorylation that facilitates EZH2 degradation and suppresses breast cancer progression." (PMID 31214490, 2019). "Silencing NF‐κB reduced EZH2 expression levels in both breast cancer cell lines, whereas the opposite effect was observed in HMECs." (PMID 31282094, 2019). "This is consistent with the pivotal role of the mTORC1/4E-BP axis in regulating EZH2 expression in ERBB2+ breast cancer." (PMID 31263101, 2019). "Taken together, this knowledge critically informs the delivery and assessment of EZH2 inhibitors in breast cancer." (PMID 31282094, 2019). "Basal-like breast cancer cells that express mesenchymal characteristics overexpress EZH2, co-ordinates with SUZ12 to form PRC2 complex and recruited to CDH1 promoter to represses E-cadherin." (PMID 35582717, 2019). "To directly address the requirement for PRC2/Ezh2 in ErbB2-driven breast cancer progression, we performed a series of experiments where Ezh2 was ablated or down-regulated in ErbB2+ breast cancer models." (PMID 31263101, 2019). "Another study suggested that the inhibition of the MAPK pathway can induce EZH2 expression in human breast cancer cells." (PMID 31727012, 2019). "In breast cancer, EZH2 acts independently of PRC2 and exerts dual functions in the presence or absence of oestrogen receptor (ER)." (PMID 31282094, 2019). "EZH2 has been reported to bind to the NOTCH1 promoter in TN breast cancer, and to bind to ERα protein." (PMID 31122254, 2019). "We also showed that AQB significantly enhanced 3-Deazaneplanocin A (DZNep), an inhibitor of the histone methyltransferase EZH2, therapy in both orthotopic breast cancer and glioblastoma patient-derived xenograft (PDX) models." (PMID 31367244, 2019). "Due to its well-known role in many cell fate decisions, many microRNAs have been shown to directly target EZH2 to modulate its expression in breast cancer." (PMID 31252590, 2019). "EZH2 was found up-regulated in melanoma, lymphoma, breast cancer, and prostate cancer, and related to promoting tumorigenesis, cell proliferation, and epithelial mesenchymal transition." (PMID 31058095, 2019). "LncRNA ANCR interacts with EZH2 to promote its phosphorylation that facilitates EZH2 degradation and suppresses breast cancer progression." (PMID 31921860, 2019). "By analyzing publicly available CHIP-seq and gene expression datasets, we aimed at describing unexplored direct targets of EZH2 in breast cancer." (PMID 30760814, 2019). "Breast cancers frequently overexpress the histone methyltransferase EZH2, the catalytic subunit of Polycomb Repressor Complex 2 (PRC2)." (PMID 31263101, 2019). "Collectively, these data confirm that Ezh2 overexpression and catalytic activity strongly promote the proliferation of ErbB2-driven breast cancer cells." (PMID 31263101, 2019). "ZNF217 has been reported to be a marker of poor prognosis in breast cancer that drives epithelial-mesenchymal transition and invasion by recruiting EZH2 to its target genes, which are marked with an H3K27me3 enrichment peak." (PMID 30764831, 2019). "EZH2, another component of the PRC2 complex, has been described as an oncogene which is deregulated in prostate and breast cancer, and implicated in cancer progression and poor prognosis." (PMID 30783079, 2019). "Our previous study proved that the 5′ domain, but not its 3′ domain, was the function domain of HOTAIR responsible for tumorigenesis and metastasis in glioblastoma and breast cancer, by recruiting and binding EZH2." (PMID 30764859, 2019). "Similar pattern of EZH2 expression was observed in MERAV breast cancer cell line expression database (Fig. 1Biii)." (PMID 30760814, 2019). "Target genes were significantly up-regulated in both MCF-7 and MDA-MB-231 breast carcinoma cell lines upon EZH2 knockdown." (PMID 30760814, 2019).
breast cancer (continued). "We show that this phosphorylation event controls EZH2 subcellular localization and is sufficient to activate the metastasis promoting function of EZH2 in breast cancer." (PMID 30022044, 2018). "EZH2 is a bona-fide oncogene in breast cancer, responsible for imparting proliferation, migration, and invasion abilities to breast cancer cells, but the mechanisms are incompletely understood." (PMID 30022044, 2018). "Similar to expression found in primary breast tumors, increased expression of EZH2 was evidenced in breast cancer cells in comparison to normal breast epithelial cells both in MERAV dataset and cells under study in the laboratory." (PMID 29940916, 2018). "Increasing study have proposed that overexpression of the EZH2 gene occurs in various human malignance such as prostate cancer, breast cancer, colorectal cancer and lung cancer." (PMID 30542123, 2018). "CUL1 regulated EZH2 expression to promote the production of cytokines, and finally significantly aggravating the breast cancer cell metastasis and angiogenesis through the PI3K–AKT–mTOR signaling pathway." (PMID 30578411, 2018). "Our study revealed that phosphorylation of EZH2 at T367 is sufficient and necessary for cytoplasmic EZH2 localization in breast cancer cells in cell lines and clinical samples of invasive carcinoma." (PMID 30022044, 2018). "Perhaps most significantly, we demonstrate that pharmacological intervention to inhibit EZH2 in an immune-competent preclinical mouse model of Luminal B breast cancer completely prevents distal metastasis." (PMID 29959321, 2018). "Through an unbiased proteomics approach, we uncover a phosphorylation-dependent ability of EZH2 to interact with cytoskeletal regulators in breast cancer cells." (PMID 30022044, 2018). "Taken together, these data show a direct interaction between p38α and EZH2, that p38α phosphorylates EZH2 at T367 in breast cancer cells and human tissues, and suggest that p38α-mediated phosphorylation reduces EZH2-mediated trimethylation of H3K27." (PMID 30022044, 2018). "The present study aims to explore the correlations of EZH2 and SMYD3 gene polymorphisms with breast cancer susceptibility and prognosis." (PMID 29089464, 2018). "Here, we report that EZH2 is regulated by p38-mediated T367 phosphorylation during breast cancer progression." (PMID 30022044, 2018). "In conclusion, we demonstrate that in response to NIC there is an enhanced expression of Myc, which in turn increases EZH2 expression and results into increased breast cancer progression." (PMID 29396474, 2018). "Though having smaller primary tumors, functional activation of EZH2 results in early metastatic invasion and most importantly; it alters the pattern of breast cancer metastasis as observed by sequential live animal imaging experiments." (PMID 29460395, 2018). "In this study, we identify a mechanism through which EZH2 mediates repression of FOXC1 to promote metastasis in Luminal B breast cancer." (PMID 29959321, 2018). "Given that the behaviour of Ezh2 is context-dependent, in this study we investigated the role of Ezh2 specifically in Luminal B breast cancer." (PMID 29959321, 2018). "The association and mechanistic link between p38-mediated phosphorylation of EZH2 at T367, cytoplasmic localization, and breast cancer progression was validated in vitro, in vivo, and in human breast cancer samples." (PMID 30022044, 2018). "EZH2 is a marker of aggressive breast cancer, overexpression of EZH2 promotes neoplastic transformation of breast epithelial cells." (PMID 30547810, 2018). "Our study shows that p38-mediated phosphorylation at T367 promotes EZH2 cytoplasmic localization and binding to cytoskeletal regulatory proteins and is essential for breast cancer metastasis." (PMID 30022044, 2018). "Our lab and other investigators have established a role for EZH2 in breast cancer proliferation, migration, and invasion." (PMID 30022044, 2018).